PEX5 (peroxisomal biogenesis factor 5)
Diseases named in the same sentence as PEX5 in open-access papers (continued):
Sharing a sentence is not in itself a finding about the gene and the disease.
cancer (6 papers, 2017 to 2024). A tumor composed of atypical neoplastic, often pleomorphic cells that invade other tissues. "Decreased PEX5 levels are associated with both the onset of cancer in vivo, and sensitivity to exogenous H2O2 addition in hepatocarcinoma model systems in vitro." (PMID 33468235, 2021). "More interestingly, seven different genes (ECH1, PEX5, MLF2, NFIX, TSPAN9, SAMD4B, and NFKBIB) were associated with another drug C646, which is a small molecule inhibitor targeting histone acetyltransferase p300, an enzyme that alters the cancer transcriptome in the lung, colon and pancreas." (PMID 29207666, 2017). "One study identified 31 differentially expressed mitochondrial proteins in irradiated cancer cells, such as solute carrier family 25 member 22 (SLC25A22) and peroxisomal biogenesis factor 5 (PEX5)." (PMID 38778409, 2024). "Among these, MLF2, COPS7A, PEX5, DDX47, STRAP and MRPL51 displayed strong correlations with USP5 in most cancer types." (PMID 37268697, 2023).
tumor (6 papers, 2015 to 2025). "PEX5 increased the tumor volume and weight, whereas the miR-31-5p agomir inhibited PEX5-induced tumor growth in vivo." (PMID 32373215, 2020). "Our findings in this study demonstrated that the miR-31-5p level is reduced in HCC and modulates tumor radioresistance through PEX5-mediated regulation of the Wnt and HR signaling pathways." (PMID 32373215, 2020). "In mammalian cells, PEX5 brings the tuberous sclerosis complex to the peroxisome, where it regulates the mTORC pathway and autophagy to suppress tumor formation." (PMID 26377801, 2015). "PEX5 protein expression was significantly increased in tumor tissues compared to paratumor tissues." (PMID 32373215, 2020). "Moreover, the miR-31-5p mimics and si-PEX5 decreased the levels of MMP2 and MMP9, key molecules mediating tumor cell invasion." (PMID 32373215, 2020).
infection (4 papers, 2020 to 2025). The state of being infected such as from the introduction of a foreign agent such as serum, vaccine, antigenic substance or organism. "After 8 days of infection, the loss of pex5, pex10, or pex33 severely reduced the fungal burden in the lungs as determined by the recovery of CFUs." (PMID 37432032, 2023). "Next, to verify if peroxisomes contribute to the formation of SCVs, we infected PEX5 KO HeLa cells, and the formation of SIFs post-infection was studied temporally." (PMID 39695325, 2025). "Depletion or loss of the Pex5 and Pex7 cytosolic receptors for PTS1 and PTS2, respectively, attenuates H. capsulatum virulence, indicating a requirement for specific peroxisome matrix proteins at different stages of infection." (PMID 37432032, 2023). "The upregulation of PEX5 and PEX13 was observed under ScYLV infection and a heat map was drawn as well in this experiment." (PMID 35774818, 2022). "Similarly, there was no change in the host LAMP1 levels after infection in the PEX5 KO cells." (PMID 39695325, 2025). "Expression of peroxisome biogenesis-related transcripts such as PEX14, PEX5, and PEX11B were not altered after 6 and 12 h of STM infection." (PMID 39695325, 2025). "Finally, we used the PEX5 KO cells and observed that the WT STM infection failed to accumulate cholesterol in the SCV." (PMID 39695325, 2025).
bacterial infection (1 paper, 2019). "Drosophila macrophage-like cell lines with no functional peroxisomes, generated by RNA interference-mediated depletion of the peroxisome biogenesis factors (peroxins) Pex5 or Pex7 (designated as PEx5-i or Pex7-i, respectively), had an impaired ROS and RNS response to bacterial infection." (PMID 31398943, 2019).
metabolic disease (1 paper, 2020). A congenital disorder (due to inherited enzyme abnormality) or acquired (due to failure of a metabolically important organ) disorder resulting from an abnormal metabolic process. "Taken together, our data suggest that peroxisomes and PEX5 would form an axis for lipid homeostasis in response to fasting signals, which might provide clues for the development of therapies against metabolic diseases associated with lipid dysregulation." (PMID 31996685, 2020). "Furthermore, mRNA level of human PEX5 gene expression was closely linked with that of lipolytic genes, including ATGL, in human GTEx analysis, implying that PEX5 may be associated with metabolic diseases, such as lipolysis dysregulation." (PMID 31996685, 2020). "Therefore, it seems that PEX5-mediated lipolysis might be a potential therapeutic target to treat human metabolic diseases involved in lipolysis dysregulation, such as NLSD." (PMID 31996685, 2020).
neoplastic disorders (1 paper, 2025). "PEX2 and other peroxins—namely, PEX5, PEX10, and PEX12—play a pivotal role in ensuring the survival of malignant cells and, consequently, emerge as prospective therapeutic targets for combating neoplastic disorders." (PMID 40487257, 2025).
PEX5 also shares sentences with these, for which no sentence is quoted: Zellweger spectrum disorders (5 papers); adrenoleukodystrophy (1); alcoholism (1); Breast Invasive Carcinoma (1); epithelial dysplasia (1); hearing loss (1); Infertility (1); liver dysfunction (1); mental disorder (1); mitochondrial disease (1); multiple sclerosis (1); Parkinson disease (1); rhizomelic chondrodysplasia punctata type 1 (1); rhizomelic chondrodysplasia punctata type 2 (1); schizophrenia (1); Seckel syndrome (1); vitiligo (1).